NLRP11 (NLR family pyrin domain containing 11)
Description:
Involved in inflammation.
Synonyms: NALP11; NOD17; PAN10; PYPAF6; CLR19.6; PYPAF7
Tractability: PROTAC: ubiquitination databases record sites on it.
Gene: Protein-coding gene on chromosome 19 (55,785,397 to 55,836,800, reverse strand). Ensembl gene ENSG00000179873.
Subcellular location (Human Protein Atlas): Cytosol
Gene Ontology:
Molecular function: RNA binding; oxidoreductase activity, acting on paired donors, with incorporation or reduction of molecular oxygen, reduced ascorbate as one donor, and incorporation of one atom of oxygen
Biological process: regulation of inflammatory response
Cellular component: cytosol; cytoplasm
Genetic constraint (gnomAD): Loss-of-function variants: 51 observed, 78.09 expected, observed/expected ratio (o/e) 0.65, 90% interval 0.52 to 0.82. The upper end of that interval is the gene's LOEUF score, 0.82, which puts it in group 3 of 6, group 1 being the genes least tolerant of losing a copy. Missense variants: 1,195 observed, 1,252.1 expected, observed/expected ratio (o/e) 0.95, 90% interval 0.91 to 1. Synonymous variants: 496 observed, 465.19 expected, observed/expected ratio (o/e) 1.07, 90% interval 0.99 to 1.15.
Homologues: Orthologues: chimpanzee NLRP11 (99% identical), macaque NLRP11 (84% identical), pig NLRP11 (53% identical), rabbit NLRP11 (53% identical). Paralogues in human: NLRP7 (28% identical), NLRP2 (27% identical), NLRP14 (25% identical), NLRP13 (23% identical), NLRP5 (22% identical), NLRP4 (21% identical), NLRP12 (21% identical), NLRP3 (20% identical), NLRP9 (20% identical), NLRP8 (19% identical), NLRP1 (18% identical), NLRC5 (17% identical), and 8 more.
Diseases named in the same sentence as NLRP11 in open-access papers:
NLRP11 is named in the same sentence as 13 diseases in open-access papers, as found by Europe PMC text mining. Sharing a sentence is not in itself a finding about the gene and the disease. The quoted sentences say what the papers report.
viral infection (3 papers, 2020 to 2021). "Because TRAF6 is involved in apoptosis after viral infection, NLRP11 can potentially inhibit apoptosis, which also ensures the survival of the host cells." (PMID 32536927, 2020). "The high expression of NLRP11 in B cells might be suggestive of a role of NLRP11 in B cell tropic viral infections." (PMID 33525590, 2021). "We demonstrate that NLRP11 can abolish IKKε-mediated phosphorylation of DDX3X, resulting in lower type I IFN induction upon viral infection." (PMID 34054816, 2021). "For example, NLRP11, a type I IFN-induced Nod-like receptor, is upregulated after viral infection and can inhibit type I IFN production." (PMID 32536927, 2020). "In our HEK293-NLRP11-eGFP cell line, we confirmed recruitment of NLRP11 to mitochondria 16 h post infection, as visualized by co-staining with AIF, however, the cellular morphology was heavily disturbed after 16 h of virus infection." (PMID 34054816, 2021).
B cell lymphoma (1 paper, 2025). "Endogenous NLRP11 interacts with ASC in the human B cell lymphoma cell line Daudi, however, the functional outcome of this interaction is unknown given that this interaction does not affect caspase‐1 activation." (PMID 39351983, 2025).
Burkitt lymphoma (1 paper, 2020). A rare form of malignant mature B-cell non-Hodgkin lymphoma. "Interestingly, the mRNA level of NLRP11 is remarkably high in Daudi cells (a human Burkitt's lymphoma cell line) and myeloid THP1 cells, whereas it is low in epithelial cell lines including HeLa." (PMID 32832566, 2020). "Interestingly, IFN-γ and IL-17A were recovered after transfection of Burkitt's lymphoma cells with siRNAs targeting NLRP11." (PMID 32832566, 2020). "Furthermore, cocultures of NLRP11-expressing Burkitt's lymphoma cells and naïve human peripheral CD4+ T lymphocytes had reduced IFN-γ and IL-17A production, whereas IL-13 and IL-10 cytokines did not change." (PMID 32832566, 2020).
cryopyrin-associated periodic syndrome (1 paper, 2022). Cryopyrin associated periodic syndrome (CAPS) defines a group of autoinflammatory diseases, characterized by recurrent episodes of systemic inflammatory attacks in the absence of infection or autoimmune disease. "NLRP11 was also necessary for inflammasome responses driven by NLRP3 mutations that cause cryopyrin-associated periodic syndrome (CAPS)." (PMID 35624206, 2022).
lymph node metastasis (1 paper, 2022). "Second, given that it is difficult to establish the presence of lymph node metastasis in many patients, the effect of the expression of AIM2, DFNB59, NLRP11 and PRTN3 on T staging was not fully investigated." (PMID 35281845, 2022).
infection (5 papers, 2021 to 2025). The state of being infected such as from the introduction of a foreign agent such as serum, vaccine, antigenic substance or organism. "Release of IL-1β during infection with M. kansasii was dependent on NLRP11, similar to the phenotype observed for M. tuberculosis-infected cells." (PMID 40272180, 2025). "At every time point, significantly lower levels of IL-1β were released from NLRP11∆N_LRR macrophages than their WT counterparts, indicating that NLRP11 is required for IL-1β release even early during infection." (PMID 40272180, 2025). "Co-localization of DDX3X and NLRP11-eGFP was also observed in HeLa-NLRP11-eGFP cells, where NLRP11-eGFP continued to stably co-localize with DDX3X over the course of 16 h of infection in the majority of cells." (PMID 34054816, 2021). "In HeLa NLRP11-eGFP cells, NLRP11 was localized in proximity to mitochondria in untreated cells and this localization pattern persisted during 16 h of SeV infection, with partial co-localization observed at 16 h post infection." (PMID 34054816, 2021). "Cell death during infection with S. flexneri was unaffected by deletion of the PYD, whereas deletion of the NACHT and LRR domains or deletion of the entire NLRP11 locus resulted in 40%–50% decreases in macrophage cell death." (PMID 40272180, 2025). "During infection with the bacterium S. flexneri, THP1 macrophages undergo caspase‐4 and gasdermin D activation in a NLRP11‐dependent manner, positioning NLRP11 as part of the non‐canonical inflammasome pathway." (PMID 39351983, 2025). "Many negative regulators, such as Tetherin, NLRC5, NLRP11, and RTP4, are induced after infection, to feedback and inhibit the production of IFNs." (PMID 37366613, 2023). "Starting at 4 h post infection, we observed increased expression levels and co-immunoprecipitation of endogenous DDX3X with NLRP11-eGFP in HEK293 cells that was strongest at 6 h and 16 h post infection." (PMID 34054816, 2021). "We next analyzed the subcellular localization dynamics of NLRP11 and DDX3X during infection with SeV by indirect immunofluorescence microscopy." (PMID 34054816, 2021). "We previously found that NLRP11 is required for activation of the non-canonical inflammasome during infection with a variety of gram-negative bacteria, including S. flexneri." (PMID 40272180, 2025). "To further examine the kinetics of NLRP11-dependent activation of the non-canonical inflammasome, we assayed IL-1β release in M. kansasii-infected WT and NLRP11∆N_LRR (Cas9) macrophages at 1, 2, 4, and 6 h of infection." (PMID 40272180, 2025). "Thus, the NACHT and/or LRR domains are required for efficient activation of the NLRP11-dependent non-canonical inflammasome during infection with S. flexneri." (PMID 40272180, 2025). "To test this hypothesis, we determined levels of IL-1β release during infection with M. tuberculosis of macrophages containing or lacking NLRP11." (PMID 40272180, 2025). "However, NLRP11 was not recruited to distinct DDX3X clusters that appeared at 16 h post infection in a minority of cells." (PMID 34054816, 2021). "Interestingly, T. gondii infection upregulated the expression of NLRC4, NLRP4, NLRP8, NLRP10, NLRP11, NLRP13, and NLRP14 mRNAs at both 4 and 8 h post-infection, but NLRP4, NLRP8, NLRP10, and NLRP11 mRNAs were significantly downregulated at 8 h post-infection compared to that at 4 h post-infection." (PMID 33712075, 2021). "The NLRP11 protein is only expressed in primates and participates in the activation of the canonical NLRP3 and non-canonical NLRP3 inflammasome activation after infection with gram-negative bacteria." (PMID 40272180, 2025).
cancer (2 papers, 2020 to 2023). A tumor composed of atypical neoplastic, often pleomorphic cells that invade other tissues. "It is noteworthy that even though adenosine and NLRP11 are both reported to have anti-inflammatory roles, the positive stimulatory effect of adenosine on NLRP11 in B lymphoblast cells might reveal a new role for NLRP11 in cancer development and progression." (PMID 32832566, 2020).
tumor (2 papers, 2023 to 2025). "Compared to vimentin, NLRP11 and vimentin‐K104Ac showed better tumor specificity, reflecting the differences between EMT‐mediated tumor cells and mesenchymal cells." (PMID 37424170, 2023). "The NLRP11/KAT7/vimentin‐K104Ac pathway may be a crucial in the inflammation‐mediated EMT in tumor cells." (PMID 37424170, 2023). "Vimentin was often highly expressed in the mesenchymal tissue rather than in the tumor, indicating that the expression of NLRP11 and vimentin‐K104Ac was more tumor‐specific." (PMID 37424170, 2023).
NLRP11 also shares sentences with these, for which no sentence is quoted: lung adenocarcinoma (1 paper); lung carcinoma (1); monocytic leukemia (1); multiple myeloma (1); retinoblastoma (1).